SMAD2 (SMAD family member 2)
Diseases named in the same sentence as SMAD2 in open-access papers (continued):
Sharing a sentence is not in itself a finding about the gene and the disease.
melanoma (continued). "Western blot analysis revealed increased TGF-β1 levels and activation of the SMAD2/3 pathway in CCNB1-overexpressing melanoma cells, whereas CCNB1 knockdown led to reduced TGF-β1 expression and inhibition of SMAD2/3 signaling." (PMID 40430484, 2025). "These regions were identified in A375 melanoma cells stimulated with TGFB1 and were bound by SMAD2/3 upon stimulus." (PMID 38874379, 2024). "Following treating melanoma cells with rCTII, there was a significant down-regulation in the expression level of SMAD2 and SMAD3 compared to untreated melanoma cells (both p < 0.01)." (PMID 33167431, 2020). "Considering the correlations among miR-200b-3p, SMAD2 and NEAT1, the aim of this study is to investigate biofunction of NEAT1/miR-200-3p/SMAD2 axis in melanoma and explore its potential as a novel biomarker and therapeutic target of melanoma." (PMID 33202380, 2020). "The qRT-PCR was performed to evaluate the expression levels of matrix metallopeptidase 3 (MMP-3), SMAD2, SMAD3, caspase-8, caspase-9, and miR-214 in order to reveal the rCTII-induced signaling pathways in melanoma." (PMID 33167431, 2020). "By means of western blot, we validated that overexpression of miR-200b-3p resulted in the suppression of SMAD2 signaling, thus weakening the EMT and cell invasion process of melanoma cells." (PMID 33202380, 2020). "Direct activation of SMAD2 and SMAD3 by ALK3 has been demonstrated in BMP2-treated melanoma and pituitary gonadotrope cells, respectively." (PMID 29416020, 2018). "Downstream of TGFβ, SMAD2 and its adaptor CITED1 regulate the amoeboidal characteristic of melanoma cells." (PMID 28137308, 2017). "Melanoma cells, however, often display constitutive activation of TGF-β signaling, and this is reflected in a steady-state presence of nuclear phospho-SMAD2." (PMID 26977879, 2016). "Since the functional role of CITED1 in melanoma is unclear, we decided to further investigate its connection to TGF-β-SMAD2-driven transcription." (PMID 26526369, 2015). "We verified these results using two other melanoma cell lines, WM1361 and WM793B, and using several oligonucleotides against SMAD2." (PMID 26526369, 2015). "We have shown that riluzole induces the phosphorylation of the cluster of serines (245/250/255) in Smad2 and serine 204 in Smad3 via GSK3, in the majority of the melanoma cell lines analyzed." (PMID 23077590, 2012). "Additionally, we demonstrated that CCNB1 promotes melanoma EMT and invasiveness through the TGF-β-SMAD2/3 signaling." (PMID 40430484, 2025). "Additionally, CCNB1 activates the TGF-β-SMAD2/3 pathway, driving EMT and enhancing melanoma invasiveness." (PMID 40430484, 2025). "Whereas TGFβ/SMAD2/3 and Hippo/YAP/TAZ have also been shown to be strong inducers of a proliferative-to-invasive phenotype switch and to promote melanoma progression and metastasis, the role of Wnt/β-catenin signaling in melanoma progression is obscured by conflicting experimental results." (PMID 34819356, 2022). "Taken together, the NEAT1/miR-200b-3p/SMAD2 signaling pathway promotes melanoma via activation of EMT, cell invasion and is related with immune responses, which provides new insights into the molecular mechanisms and therapeutic targets for melanoma." (PMID 33202380, 2020). "The current study has demonstrated that rCTII might substantially stimulate the apoptosis pathways, especially the intrinsic pathway, inhibit the expression of mir-214 and MMP-3, and suppress the TGF-β pathway via down-regulating SMAD2 and SMAD3 in melanoma." (PMID 33167431, 2020). "For instance, high amplification of SMAD2 was related to low infiltrates levels of dendritic cells, macrophages and CD8+ T cells, thus forming an immune-suppressive microenvironment and making ways for the immune escape of melanoma cells." (PMID 33202380, 2020).
melanoma (continued). "Nelfinavir increased the amount of SMAD2 and consequently nuclear phospho-SMAD2 in melanoma cell lines in the absence of exogenous TGF-β, and, importantly, this correlated with the reduction in PAX3 and MITF expression." (PMID 26977879, 2016). "Because we had identified the SMAD2/4/SKI complex as relevant for the inhibitory action of nelfinavir on PAX3 transcription, and nelfinavir counteracted the MAPKi-induced tolerance in melanoma cells, we wanted to identify the link between the SMAD/SKI suppressor complex and MAPK signaling." (PMID 26977879, 2016). "Next, we determined whether treatment of melanoma cells with recombinant CR-1 induces the activation of c-Src and Nodal/ALK4/Smad-2 pathways." (PMID 21863025, 2011). "Interestingly, we found that blocking Smad3 and Smad4 gene expression but not Smad2 significantly increased melanoma tumorsphere formation in both cell lines." (PMID 38201651, 2024). "In addition, Spearman’s correlation analysis depicted a negative correlation between expressions of miR-200b-3p and SMAD2 in the 18 melanoma tissue samples (R=−0.7234, P < 0.01)." (PMID 33202380, 2020). "Now that previous literature has illustrated the participation of miR-200 family in EMT and SMAD2 is regarded as the subsequent effector of the TGF-β signaling pathway in EMT, it’s reasonable to infer that the NEAT1/miR-200b-3p/SMAD2 axis can regulate the EMT process of melanoma cells." (PMID 33202380, 2020). "In addition, in the UACC930 melanoma cell line, where the expression of GRM1 protein is not detectable, the induction of Smad2 and Smad3 linker phosphorylation in the presence of riluzole is comparable to that of the other melanoma cell lines that express GRM1." (PMID 23077590, 2012). "ERK can regulate SMAD function at various levels in TGF-β signaling, but we did not detect any effect of MEK inhibition on SMAD2 steady state or TGF-β-induced nuclear localization, or TGF-β-stimulated transcription of SPARC or VEGF in melanoma cells." (PMID 26977879, 2016). "We obtained the same results in C8161 and UACC930 human melanoma cell lines; SB431542 did not inhibit riluzole-induced Smad2 and Smad3 linker phosphorylation in these lines." (PMID 23077590, 2012).
cervical carcinoma (33 papers, 2013 to 2025). A carcinoma arising from either the exocervical squamous epithelium or the endocervical glandular epithelium. "Rs4940086 heterozygous genotype (T/C) of SMAD2 was associated with a 3.89-fold higher risk of developing cervical cancer (p = 0.001, AOR 3.89, 95% CI 1.777–8.513)." (PMID 37685308, 2023). "Its effect on the expression of EMT- and TGF-β1/Smad2/3 pathway-related proteins and the growth of cervical cancer xenograft was also examined to explore the underlying mechanism." (PMID 35975844, 2023). "A recent candidate gene study investigated the association between SMAD2 gene polymorphisms and cervical cancer among women in a Bangladeshi population using rs4940086 tagSNP and found that its heterozygous genotype (T/C) was associated with a significantly higher risk of cervical cancer." (PMID 38200081, 2024). "The results suggest that polymorphic variants of SMAD2, particularly rs4940086, may increase cervical cancer susceptibility in Bangladeshi women." (PMID 37685308, 2023). "In addition, a clinical study found that single nucleotide polymorphisms (SNPs) in SMAD2 (rs4940086 and rs8085335) have an impact on the development of cervical cancer risk in the Bangladeshi population." (PMID 37685308, 2023). "“miR-484 suppresses proliferation and epithelial-mesenchymal transition by targeting ZEB1 and SMAD2 in cervical cancer cells” published in Cancer cell international was retracted as a result of concerns/issues about data and duplication of image." (PMID 38984306, 2024). "Sildenafil inhibits the proliferation, invasion ability, and EMT of human cervical cancer cells by regulating the TGF-β1/Smad2/3 pathway." (PMID 35975844, 2023). "The expression of TGF-β1, TβRI, p-Smad2 and p-Smad3 was significantly enhanced in cervical cancer samples and cervical cancer cell lines." (PMID 35975844, 2023). "The levels of transforming growth factor-β1 (TGF-β1), transforming growth factor-β type I receptor (TβRI), phosphorylated (p-) Smad2 and p-Smad3 in cervical cancer samples were measured." (PMID 35975844, 2023). "The expression of TGF-β1, TβRI, p-Smad2 and p-Smad3 were analyzed in a total of 30 cervical cancer and normal tissue samples." (PMID 35975844, 2023). "As demonstrated in Fig. (3A-D), the expression of TGF-β1, TβRI, p-Smad2 and p-Smad3 was significantly enhanced in cervical cancer samples (p<0.05)." (PMID 35975844, 2023). "They demonstrated that FAD104, a positive regulator of adipocyte differentiation, suppresses the TGF-β-mediated EMT in cervical cancer cells, with upregulation of Smad1/5/8 phosphorylation and downregulation of Smad2/3 phosphorylation." (PMID 35580109, 2022). "The targeting of ZEB1 and SMAD2 by miR-484 was predicted in our analysis and is reported to suppress proliferation and epithelial-mesenchymal transition in cervical cancer." (PMID 34547721, 2021). "MiR-486 is known to drive tumorigenesis by targeting multiple negative regulators of PTEN/PI3K/Akt, FOXO, and TGF-β/Smad2 signaling in cervical cancer and prostate cancer cells." (PMID 32155804, 2020). "Overall, these data strongly supported that GDF15 knockdown suppressed migration and invasion of cervical cancer cells through the TGF‐β/Smad2/3 signaling pathway." (PMID 33098235, 2020). "In summary, we report here that GDF15 knockdown inhibits migration and invasion of cervical cancer cells in vitro through the TGF‐β/Smad2/3/Snail1 pathway." (PMID 33098235, 2020). "Previous study showed that overexpression of SMAD2 promoted cervical cancer cell growth by facilitating the G1/S phase transition." (PMID 33330073, 2020). "Knockdown of GDF15 markedly affects epithelial–mesenchymal transformation‐related gene expression and suppresses the migration and invasion abilities of cervical cancer cells through the transforming growth factor‐β/Smad2/3/Snail1 pathway." (PMID 33098235, 2020). "Our finding illustrated that GDF15 regulated the TGF‐β/Smad2/3 signaling pathway in cervical cancer cells." (PMID 33098235, 2020).
cervical carcinoma (continued). "In conclusion, our study showed that silencing of GDF15 significantly inhibits the progression of cervical cancer through the TGF‐β/Smad2/3/Snail1 pathway." (PMID 33098235, 2020). "While it is well known that TGF-β-induced EMT is regulated by many factors, such as Smad2/3, Snail, Slug, and Twist, the underlying mechanisms involved in TGF-β-mediated EMT in cervical cancer are not fully understood." (PMID 31546735, 2019). "In cervical cancer, mutations or loss of TGFβ downstream effectors SMAD2 and SMAD4 are common, and loss of nuclear SMAD2 and SMAD4 is associated with poor survival." (PMID 28219480, 2017). "Smad2 mRNA expression has been found reduced in 22% of cervical carcinomas, as compared to normal cervix, while another study reported “weak” Smad2 protein levels in 33% of cervical tumors." (PMID 24047375, 2013). "Smad2/3 signalling was found to be involved in TGF-β-induced EMT in cervical cancer cell lines." (PMID 36766756, 2023). "In addition, the protein levels of TGF-β1 and TβRI and the phosphorylation levels of Smad2/3 (p-Smad2 and p-Smad3) were significantly increased in HeLa and SiHa cells, indicating that the TGF-β1/Smad2/3 pathway was activated in cervical cancer." (PMID 35975844, 2023). "Based on the earlier data, we concluded that GDF15 silencing could suppress the migration of cervical cancer cells via regulating the TGF‐β/Smad2/3/Snail1 pathway." (PMID 33098235, 2020). "To further investigate whether GDF15 affected cervical cancer metastasis through mediating the TGF‐β/Smad2/3 signaling pathway, we treated HT‐3 and HeLa cells with Smad2/3 activator TGF‐β1 (10 ng·mL−1) after shGDF15 transfection." (PMID 33098235, 2020). "Another report reviewed that cell cycle progression was regulated by the SMAD2/SMAD3 pathway, which is consistent with the study that SMAD2 overexpression could promote cervical cancer cell growth by facilitating the G1/S phase transition." (PMID 26356815, 2015). "Resent report indicated that downregulated SMAD2 expression could suppress the G1/G0 arrest in Cervical Cancer Cells." (PMID 26356815, 2015). "Furthermore, whether the relationship of miR-484 indirectly regulating SMAD2 in cervical cancer tissues also exists with cardiac tissues or even involved in MI/R remains to be further tested." (PMID 35356223, 2022). "In addition, miR-212/132 functions as tumor suppressor by targeting Smad2 in cervical cancer." (PMID 31906769, 2020). "Furthermore, we explored whether GDF15 modulated cervical cancer cell migration through mediating the TGF‐β/Smad2/3 signaling pathway." (PMID 33098235, 2020). "Previous study identified miR‐484 as an inhibitor of cell proliferation and invasion by targeting ZEB1 and SMAD2 in cervical cancer cells, revealing that ZFAS1 may promote cell proliferation and invasion via sponging miR‐484 to modulate the expression of ZEB1 and SMAD2." (PMID 30288832, 2019). "Additionally, bta-miR-484 has been observed to prevent cell proliferation and epithelial–mesenchymal transition process by targeting both ZEB1 and SMAD2 genes, thus functions like a tumor suppressor and may serve as a prospective biomarker for cervical cancer." (PMID 30149509, 2018). "Disruption of the TGFβ signaling pathway and diminished SMAD2 phosporylation are well documented in HPV16-immortalized human keratinocytes and human cervical cancers." (PMID 26701206, 2016). "To confirm whether the TGF-β1/Smad2/3 pathway was activated in cervical cancer cells, we examined the expression of TGF-β1 and TβRI in cervical cancer cell lines (HeLa, HT-3, C33A, SiHa and U14) and HCerEpiC cells." (PMID 35975844, 2023). "Previous in vitro culture systems have shown that MAP3K19 siRNA or MAP3K19 inhibitors reduced the TGF-β-induced phospho-Smad2/3 nuclear translocation in an A549 human lung adenocarcinoma cell line, THP-1 human monocytes/macrophages, Human Embryonic Kidney cells, and HeLa cervical cancer cells." (PMID 37998736, 2023).
cervical carcinoma (continued). "A research uncovered that reduced miR-484 expression levels in clinical cervical cancer specimens and cell lines could restore ZEB1 and SMAD2, key transcription factors of epithelial-mesenchymal transition (EMT), inducing CC malignant behavior." (PMID 35356223, 2022). "Together with the results of the in vitro experiments, these findings indicated that sildenafil may inhibit the proliferation and invasion/migration ability of human cervical cancer cells, as well as inhibit the EMT process in HeLa cells by regulating the TGF-β1/Smad2/3 pathway." (PMID 35975844, 2023).
liver cancer (33 papers, 2011 to 2025). An epithelial or non-epithelial malignant neoplasm that arises from the liver. "Thus, liver cancer cells appear to hijack Smad2/3 and Smad4 for CSCs, and this process is closely associated with oncogene cyclin D1 regulation." (PMID 28415588, 2017). "Downregulation of TGFBR3 expression can promote the EMT process of liver cancer by inducing activation of the SMAD2 and AKT pathways, thus promoting its progression." (PMID 39404708, 2024). "In fact, CHI3L1 can modulate TGF-β signaling in liver cancer through the regulation of SMAD Family Member-2 (SMAD-2) and SMAD-364." (PMID 38177294, 2024). "The exact mechanisms by which Smad2 and Smad3 exert their effects in liver cancer are still being studied." (PMID 37790613, 2023). "It is important to note that the TGF-β1/smad pathway and the roles of Smad2 and Smad3 in liver cancer are complex and multifaceted, and further research is needed to fully understand their mechanisms of action and potential therapeutic implications." (PMID 37790613, 2023). "Liver cancer patients with high SMAD2 expression had significantly shortened survival times in TCGA." (PMID 37790613, 2023). "Smad2 and Smad3 have been found to have both tumor-suppressive and tumor-promoting effects in liver cancer, depending on the context." (PMID 37790613, 2023). "In summary, we demonstrated for the first time that proHp suppresses the TGF-β-induced EMT and cell invasion in vitro by enhancing Smad1/5 activation and suppressing the Smad2/3 signaling pathway in SK-Hep1 liver cancer cells." (PMID 35580109, 2022). "Collectively, these results indicated that SOX9 and SMAD2 acted downstream of YAP-signaling potentially increase transcriptional diversity in liver cancer patients." (PMID 35322024, 2022). "CHI3L1 can also regulate liver cancer potentially by regulating the TGF-β signaling pathways with activating kinase to phosphorylate SMAD2 and SMAD3." (PMID 34991559, 2022). "Previous studies have shown that FHLs promoted phosphorylation of Smad2/3 and directly interacted with them, leading to nuclear accumulation of Smad complex in liver cancer." (PMID 34150617, 2021). "Experiments have shown that this program can effectively increase the activity of the TGF-β1/Smad2 signaling pathway, significantly reduce the proliferation of liver cancer cells, and the tumor inhibition rate can reach 35%." (PMID 34323647, 2021). "In order to explore the effect of propofol on the proliferation and apoptosis of liver cancer cells through the TGF-β1/Smad2 signaling pathway, detailed experimental analysis was carried out." (PMID 34323647, 2021). "Based on this, this paper studies the effect of propofol on the proliferation and apoptosis of liver cancer cells through the TGF-B1/Smad2 signaling pathway, and explores the proliferation, adhesion and apoptosis of cancer cells in patients with propofol." (PMID 34323647, 2021). "Wang mentioned in the article that the propofol drug propofol can proliferate and apoptosis of liver cancer cells through the TGF-β1/Smad2 signaling pathway, and the effect is very obvious." (PMID 34323647, 2021). "This article mainly studies the effect of propofol on the proliferation and apoptosis of liver cancer cells through the TGF-β1/Smad2 signaling pathway." (PMID 34323647, 2021). "The experimental group shows that in rats the weight of the transplanted tumor is significantly reduced, and it can be seen that the Smad2 signaling pathway can indeed release inhibitors to reduce the proliferation of liver cancer cells." (PMID 34323647, 2021). "In this study, we found that LINC01234 knockdown downregulated the expression of p-Smad2, p-Smad3 in liver cancer cells and increased the level of Smad4 in Cytoplasm of Huh-7 cells." (PMID 33178601, 2020). "SMAD2 is a key player for the TGF-β signaling pathway in the initiation of the hepatic cancer, where it induces the EMT and CSC-like properties and markers." (PMID 30944375, 2019).